LAG3 (lymphocyte activating 3)
Diseases named in the same sentence as LAG3 in open-access papers (continued):
Sharing a sentence is not in itself a finding about the gene and the disease.
diabetes (21 papers, 2014 to 2024). "Accelerated diabetes with increased islet‐infiltration by autoreactive T cells was observed in LAG‐3‐deficient non‐obese diabetic (NOD) mice in independent studies." (PMID 39560030, 2024). "The interaction between LAG-3 and stable peptide-MHC class II complexes (pMHCII) induces T cell suppression and thereby inhibits diabetes progression in NOD mice with LAG-3 deficiency." (PMID 36704045, 2022). "Induce T cell suppression and thereby inhibit diabetes progression in NOD mice with LAG-3 deficiency." (PMID 36704045, 2022). "LAG-3 also plays a role in the proliferation and function of Tregs and may be implicated in the development of other complications of diabetes or immune-mediated renal disease." (PMID 38812511, 2024). "However, LAG-3 blockade or LAG-3 deficiency accelerates diabetes in the predisposed NOD mice." (PMID 26347741, 2015). "Inhibiting LAG3 in CD8+ T cells also results in accelerated diabetes in NOD mice, indicating that both PD1 and LAG3 restrain T cells in the islets." (PMID 38533515, 2024). "An in vivo experimental study demonstrated that 100% of LAG3 knockout mice develop diabetes with a peak insulin level, suggesting rapid destruction of pancreatic β cells." (PMID 37880788, 2023). "If Lag3 is an inhibitory receptor interfering with Treg cell function as observed in diabetes, targeting Lag3 in intratumoral Treg cells will enforce the function, further limiting anti-tumor immunity." (PMID 35359918, 2022). "In our study, PFK15 treatment led to increased PD-1 and LAG-3 expression on CD4+ T cells that correlated with protection from diabetes onset." (PMID 34163475, 2021). "Evidence of the importance of IRs is underscored by the accelerated diabetes observed in the absence or blockade of PD-1 or LAG-3 in NOD mice." (PMID 34163475, 2021). "A recent approach of co-transfer of CD4 + CD49b + LAG3 + Tr1 cells along with diabetic splenocytes showed a significant decrease in diabetes in NOD mice." (PMID 33154424, 2020). "Co-transfer of 1 x 105 CD4+CD49b+LAG3+ Tr1 cells from vaccine-treated animals with diabetic splenocytes (1 × 106) resulted in a significant decrease in diabetes." (PMID 30863412, 2019). "Even a partial reduction in LAG-3 expression led to rapid diabetes disease development." (PMID 34067904, 2021). "In Non-Obese Diabetic mice, the absence of LAG-3 is associated with a progression of diabetes." (PMID 38812511, 2024). "LAG-3 expression could effectively prevent some autoimmune disorders, as it has been described as limiting the pathogenic potential of CD4 and CD8 T cells in the initiation phase and the driving phase of diabetes onset." (PMID 34067904, 2021). "Moreover, our research has revealed that patients with diabetes who have developed DR, DPN, or other glomerular nephropathy exhibit down-regulation of LAG-3 on peripheral T lymphocyte compared to controls." (PMID 38812511, 2024). "Previous studies have shown that the T allele of LAG3 rs870849 is a protective factor for ITP severity, while it is unlikely to affect type 1 diabetes mellitus susceptibility." (PMID 35265454, 2022). "PFK15 treatment has been reported to increase the expression of PD-1 and LAG-3(lymphocyte-activation gene 3) on CD4 T cells and prevent the development of diabetes via inhibiting glycolysis utilization of diabetogenic CD4 T cells and reducing T cell responses to β cell antigen." (PMID 36704045, 2022). "While vaccination with the combination therapy increases CD4+CD49b+LAG3+ Tr1 cells, it was not clear if these cells carried specificity to a diabetes relevant antigen." (PMID 30863412, 2019). "Similarly, mice without Lymphocyte-activation gene 3 (LAG3) do not develop spontaneous disease but have accelerated diabetes onset when bred onto a NOD background." (PMID 30349540, 2018).
diabetes (continued). "Bettini and colleagues indicated that absence of LAG-3 increased islet antigen (Ag)-specific T cell infiltrate into pancreatic islets of non-obese diabetic (NOD) mice at a younger age and they developed significantly accelerated diabetes with 100% incidence." (PMID 34975855, 2021).
liver cancer (21 papers, 2018 to 2025). An epithelial or non-epithelial malignant neoplasm that arises from the liver. "Recent studies have recognized that the overexpression of immune checkpoints, such as PD‐L1, CTLA4, and LAG3, is associated with poor prognosis in liver cancer, which is consistent with our result of the Lnc_high group having poor DFS and OS." (PMID 35040184, 2022). "FGL1 inhibited CD8+ T and NK cell functions via its receptor LAG-3, explaining to some extent why the liver has high susceptibility to primary tumors and is a common site of tumor metastasis and providing a strategy of checkpoint targeting for liver cancer immunotherapy." (PMID 38973608, 2024). "Our study found that liver cancer patients in the high-risk group had high expression of some immune checkpoints (PD-1, PD-L1, CTLA4, B7-H3, VSIA, LAG3 and TIGIT)." (PMID 36081999, 2022). "FGL1 was found to be over‐expressed in human liver cancer as a major ligand of Lag‐3 which is responsible for its T‐cell inhibitory function, and had a link with a poor prognosis and therapeutic outcome." (PMID 32810392, 2020). "Further clinical trials about Tim-3, Lag-3 or TIGIT blockers should be performed in liver cancer treatment." (PMID 29843754, 2018). "Whether FGL1, a new ligand of LAG-3, has therapeutic potential for liver cancer still needs to be investigated." (PMID 38973608, 2024). "In conclusion, hepatocyte-derived FGL1 played critical immunoregulatory roles in the liver and contributed to liver metastasis and tumor growth by inhibiting CD8+ T and NK cell functions via the receptor LAG-3, providing a new strategy for liver cancer immunotherapy." (PMID 38973608, 2024). "The PDGF/PDGFRB signaling we observed in the low MC region activates the downstream lymphocyte-activation gene 3 (LAG3)/fibrinogen-like protein 1 (FGL1) immunosuppressive axis, adding complexity to liver cancer immune evasion analysis." (PMID 39015573, 2024). "In order to identify novel immune biomarkers from the TCGA-LIHC and examine associated expression with established immune biomarkers for T cell activation with an immune checkpoint inhibitor in liver cancer, this study examined PDCD1, CTLA4, HAVCR2, and LAG3." (PMID 38248311, 2023). "These research preclinical findings back up the exploration of TIM3, LAG-3, and PDCD1 inhibition in liver cancer cases." (PMID 38248311, 2023). "Several other inhibitory receptors, including T-cell immunoglobulin- and mucin-domain-containing molecule-3 (Tim-3) and LAG-3, are also upregulated on TAA-specific CD8+ T-cells in various cancer types, and are also involved in progression of liver cancer." (PMID 29843754, 2018). "Inhibition of the USP7 by P5091 disrupts a positive feedback loop involving PRDM1-mediated upregulation of FGL1, thereby enhancing CD8+ T cell activity and suppressing liver cancer growth; combined USP7 and LAG3 blockade demonstrates superior antitumor efficacy compared to LAG3 inhibition alone." (PMID 41359051, 2025). "According to in vitro and in vivo experiments, FGL1 leads to TRM suppression in HCC, and blockade of the LAG3 and FGL1 pathways might restore the TRM-mediated anti-tumor response in liver cancer." (PMID 36993960, 2023). "As the expression of LAG3 is low in the liver, the FGL1/LAG3 interaction may not contribute to liver cancer." (PMID 40832769, 2025). "Liver tumor-infiltrating lymphocytes also express higher levels of lymphocyte activation gene-3 (LAG-3), T cell immunoglobulin-3 (TIM-3), and T cell immunoglobulin and ITIM domain (TIGIT), providing support for exploring the next generation of checkpoints in liver cancer immunotherapy." (PMID 38973608, 2024). "Our previous study found that traditional Chinese medicine could improve the tumor microenvironment of patients to treat liver cancer and speculated that the immune checkpoints CTLA-4, LAG-3, and BIRC5 are the key targets for activating immune cells to treat liver cancer." (PMID 34744733, 2021).
triple-negative breast carcinoma (21 papers, 2019 to 2026). An invasive breast carcinoma which is negative for expression of estrogen receptor (ER), progesterone receptor (PR), and human epidermal growth factor receptor 2 (HER2). "ICB targeting LAG3 and PD-L1 simultaneously inhibits metastatic progression in preclinical triple negative breast cancer (TNBC) mouse models of NF1-, TSC1- or TGF-β RII- deficient tumors." (PMID 38997291, 2024). "ICB targeting LAG3 and PD-L1 in triple-negative breast cancer (TNBC) mouse models with NF1, TSC1, or TβRII deficient tumors showed significant efficacy." (PMID 38997291, 2024). "This study aimed to evaluate the expression of lymphocyte activation gene-3 (LAG-3) and its relationship with programmed cell death ligand-1 (PD-L1) in triple-negative breast cancer (TNBC)." (PMID 36945923, 2023). "One subset of exhausted CD8+ T cells named LAG3/c8 in triple-negative breast cancer (TNBC) had higher expression of PD-1, LAG3, and the ligand-receptor pair of CD27 and CD70, known to enhance T cell cytotoxicity." (PMID 35440049, 2022). "In contrast, within the subgroup of triple-negative breast cancers, LAG-3 was shown to be a significant prognostic factor regarding RFS (p = 0.01, n = 335) and OS (p = 0.037, n = 132): a higher LAG-3 expression was associated with a better outcome." (PMID 36289918, 2022). "We also analyzed a triple negative breast cancer dataset finding the co-expression of the immuno-regulatory proteins, PD1, PD-L1, Lag3 and IDO, to be associated with disease recurrence." (PMID 35748713, 2022). "T cells from triple negative breast cancer patients were enriched in vitro and activated to express PD1, lymphocyte-activation gene 3 (LAG3), mucin-domain containing-3 (TIM3) immune checkpoint receptors then cell membranes were isolated and mixed with NPs." (PMID 40292310, 2025). "It was found that in triple-negative breast cancer (TNBC), LAG-3 was significantly upregulated and may be considered a potential biomarker." (PMID 36077354, 2022). "For example, when examining infiltrated triple-negative breast cancer (TNBC) tumors, we found the median ratio of PD-1+ to PD-L1+ immune cells to be near unity and the prevalence of PD-1 or Lag3 positive lymphocytes to be 13.9% and 5.5% on average, respectively." (PMID 35058616, 2022). "We analyzed a MIBI triple-negative breast cancer (TNBC) dataset studying the co-expression of two sets of functional markers, (a) HLA-DR, CD45RO, H3K27me3, H3K9ac and HLA-Class-1, and (b) PD1, PD-L1, Lag3 and IDO, which are also known as immuno-regulatory proteins (IRP’s)." (PMID 35748713, 2022).
mesothelioma (19 papers, 2017 to 2026). A usually malignant and aggressive neoplasm of the mesothelium which is often associated with exposure to asbestos. "In a preclinical mesothelioma model, dual blockade with anti-PD-L1 and anti-LAG-3 delayed tumor growth and improved survival compared with controls, although the combination did not outperform anti-PD-L1 monotherapy." (PMID 41463268, 2025). "A phase 2 study evaluated the combination of ieramilimab, a humanized anti-LAG-3 antibody with spartalizumab (an anti-PD-1 antibody) for patients with select advanced solid malignancies, including mesothelioma." (PMID 39409190, 2024). "Additionally, increased LAG3 expression was associated with better survival outcome in UVM, LGG, and KIRC but worse in SKCM, thyroid carcinoma (THCA), and mesothelioma (MESO)." (PMID 36354714, 2022). "Intriguingly, analysis of The Cancer Genome Atlas (TCGA) dataset indicates that high mRNA expression of LAG-3 is associated with better OS, and a recent analysis suggests that high LAG-3 mRNA expression is a common feature in mesothelioma at both the mRNA and protein level." (PMID 33952230, 2021). "For example, PD-1/PD-L1-targeted immunotherapy may be preferentially considered for Lung-AC MPE patients, while LAG-3 inhibitory therapy may be suitable for mesothelioma patients." (PMID 31817531, 2019). "In this consideration, besides anti-PD-1, other immune checkpoint inhibitors such as anti-BTLA, anti-CTLA-4, anti-Siglec-10, anti-TIGIT, anti-TIM-3, anti-LAG-3 could be tested in combination to investigate their suitability for enhancing Vδ2 T cell efficacy in this mesothelioma model." (PMID 38077396, 2023). "In parallel, other inhibitory receptors such as LAG-3 and TIM-3 are frequently upregulated on TILs in mesothelioma, reflecting an exhausted immune state." (PMID 41463268, 2025). "The trials on new immune checkpoint targets such as anti-VISTA, OX40, LAG-3, and TIM-3 are all in their infancy, with data coming from basket trials or ongoing phase 1 trials, thus more data on mesothelioma patients specifically are needed." (PMID 37445594, 2023). "To our knowledge, we are the first to describe the expression of TIM-3 and LAG-3 on CD4+ and CD8+ T cells and CD3-CD56+ NK cells in effusions of mesothelioma patients." (PMID 29163783, 2017). "Although no expression of LAG-3 is typically seen on mesothelial cells, high levels have been reported in pleural effusions of patients with mesothelioma." (PMID 39409190, 2024). "Even though LAG-3 is not directly expressed by cancer cells, it is usually detected in pleural effusions of mesothelioma patients and tumor infiltrated lymphocytes in pleural effusions." (PMID 35785199, 2022). "IRF3 expression and the immune checkpoint genes significantly correlated with LAG3 and LGALS1 (Galectin) genes expression in mesothelioma cells, while positive correlation was found between IRF3 and HAVCR2 (TIM-3) or PDCD1LG2 (PD-L2) expression in monocytes/macrophages." (PMID 34768716, 2021). "Additional co-inhibitory and co-stimulatory molecules such as T-cell immunoglobulin and mucin-domain containing-3 (TIM3, also known as HAVCR2), lymphocyte activation gene 3 (LAG3) and inducible T cell co-stimulator (ICOS) are being investigated in mesothelioma." (PMID 32226777, 2020). "In summary, these findings show that following autologous DC therapy in mesothelioma patients the frequencies of circulating CD4 T cells expressing HLA-DR, PD-1 or ICOS, as well as CD8 T cells expressing the co-inhibitory receptor LAG3 are significantly increased." (PMID 30245692, 2018). "Anti-LAG-3 and anti-PD-1 ICB could be a beneficial treatment option to combine with anti-metabolite chemotherapy for cancers that currently have low response rates to ICB, like mesothelioma." (PMID 39343508, 2024).
mesothelioma (continued). "Regarding checkpoint inhibitors (PD-1 and PD-L1) and exhaustion markers (TIM3, LAG3, and IDO), which are targets of immunotherapies and thus are also currently of great interest also in mesothelioma research, we did not observe any associations with patient survival." (PMID 35795056, 2022). "In a non-mesothelioma setting, a patient with SMARCB1-deleted, metastatic, poorly differentiated chordoma was treated with Tazemetostat (EZH2 inhibitor), and had a significant increase in intratumoral and stromal infiltration by immune cells expressing checkpoint regulators PD-1 and LAG-3." (PMID 33952230, 2021). "In contrast, Salarolgio and colleagues reported that increased frequencies of CD4+PD-1+, CD4+TIM-3+, CD4+LAG-3+ T cells within tumour tissue, but not MPE correlated with poor survival in mesothelioma patients." (PMID 41574275, 2026). "We have recently described the absence of LAG-3 and the presence of TIM-3 on tumor cells and stromal immune cells in mesothelioma tissue." (PMID 29163783, 2017).
cervical cancer (18 papers, 2020 to 2026). A primary or metastatic malignant neoplasm involving the cervix. "The results revealed that low expression of LAG3 was linked to a poor prognosis in cervical cancer (p = 0.0027), while high expression of IL‐1β was also associated with poor prognosis (p = 0.0014)." (PMID 41025546, 2025). "To investigate the role of LAG3 in cervical cancer proliferation in vivo, we established a subcutaneous tumor model." (PMID 41025546, 2025). "Taken together, these findings support the conclusion that LAG3 inhibits the proliferation of cervical cancer cells." (PMID 41025546, 2025). "We then performed transwell assays, which showed that LAG3 knockdown increased the migratory and invasive capabilities of cervical cancer cell lines, while LAG3 overexpression reduced these capabilities." (PMID 41025546, 2025). "Further, our findings position LAG3 as a therapeutic target, which provides a rationale for developing LAG3 agonists in cervical cancer." (PMID 41025546, 2025). "Functional experiments demonstrated that LAG3 overexpression suppressed cervical cancer cell proliferation, migration, and tumor growth, while its knockdown promoted malignant phenotypes." (PMID 41025546, 2025). "A phase I study with the PD-1 and LAG-3 targeting bispecific molecule, tebotelimab, demonstrated efficacy in a small cohort of patients with cervical cancer." (PMID 39888529, 2025). "Studies have found that the molecular typing of pyroptostic‐related genes (PRGs) in cervical cancer can predict prognosis, and the GNAZ/LAG3/IL1B/CA2/SPRR3 risk scoring model has been constructed." (PMID 41025546, 2025). "LAG-3, overexpressed in cervical cancer tissues, suppresses cytotoxic T cell activity and amplifies Treg-mediated immunosuppression." (PMID 40808954, 2025). "To investigate the effect of LAG3 on cervical cancer cell biology, we first optimized the dose–response of siLAG3 transfection in Hela and Siha cells and verified the overexpression efficiency of the LAG3 plasmid." (PMID 41025546, 2025). "Further investigations are needed to elucidate the precise role of LAG-3 in cervical cancer progression and to validate the safety and efficacy of LAG-3 inhibitors in clinical settings." (PMID 40808954, 2025). "This study establishes a novel PRG‐based prognostic model and highlights LAG3 as a key tumor suppressor and immune regulator in cervical cancer." (PMID 41025546, 2025). "LAG-3 is another immune checkpoint molecule expressed on T cells, with emerging therapeutic relevance in cervical cancer." (PMID 40808954, 2025). "Immunofluorescence experiments revealed that increased LAG3 expression reduced the proliferative capacity of cervical cancer cells, while knockdown of LAG3 enhanced their proliferative capacity." (PMID 41025546, 2025). "To further explore the role of LAG3 in the immune microenvironment of cervical cancer, we obtained the single‐cell datasets GSE171894 and GSE168652 from the GEO database." (PMID 41025546, 2025). "The expression of LAG-3 was detected in TILs in cervical cancer, with intensity levels ranging from 100 to 57.5%, where an association with variable PD-1 expression was also found." (PMID 36077354, 2022). "Upregulation of additional immune checkpoints including lymphocyte-activation gene 3 (LAG-3) has been seen in multiple cancers including cervical cancer and is thought to play a role in adaptive resistance to ICI." (PMID 34640541, 2021). "DUET-4 trial of the bispecific antibody targeting CTLA-4 and LAG-3 alone or in combination with pembrolizumab is an early phase study of patients with advanced malignancies including cervical cancer (NCT03849469)." (PMID 34640541, 2021). "LAG-3 may inhibit the function of CD8+ T cells in the cervical cancer TME, thereby promoting the progression of cervical cancer." (PMID 41685310, 2026).